NLRP3 (NLR family pyrin domain containing 3)
Diseases named in the same sentence as NLRP3 in open-access papers (continued):
Sharing a sentence is not in itself a finding about the gene and the disease.
gout (continued). "Oral NLRP3 inhibitors have been developed and are tested on patients with gout." (PMID 34135690, 2021). "Likewise, the administration of monosodium urate (MSU) crystals triggers an acute inflammatory condition via NLRP3 inflammasome activation mimicking human gout pathology, including joint inflammation and arthritis." (PMID 33803783, 2021). "The occurrence of MSU-mediated gout inflammation is a complex process, including the phagocytosis of autoimmune cells, the negative regulation of inflammatory mediators such as NLRP3 inflammasomes, Toll-like receptors and IL-1β, and the formation of aggregated neutrophil extracellular traps, etc." (PMID 33935726, 2021). "NLRP3 inflammasome inhibitor was also shown to suppress gouty arthritis in mice." (PMID 34803702, 2021). "NLRP3 inflammasome (NLRP3, apoptosis-associated speck-like protein (ASC), and caspase-1) signaling is involved in the pathogenesis of interleukin (IL)-1β-mediated gouty arthritis." (PMID 33935726, 2021). "Collectively, these findings show that TRIM65 decreased disease severity in multiple mouse models of NLRP3-dependent acute inflammatory diseases (LPS-induced systemic inflammation and MSU-induced peritonitis and gouty arthritis) via suppression of the NLRP3 inflammasome." (PMID 34512673, 2021). "Gout is considered not only a dysmetabolic disorder, but is classified as an inflammatory disease, for which the activation of the innate immune system, in particular the NLRP3 inflammasome pathway, plays a central role in its pathogenesis." (PMID 33926105, 2021). "Therefore, the results indicated that TF alleviated LPS/MSU induced cellular gout model via regulation of NLRP3/ASC/Caspase-1 signaling pathway." (PMID 34079466, 2021). "Our current data demonstrated that BRD4 suppression could partially counteract the severity of pyroptotic death in acute gouty arthritis via the BRD4/NF-κB/NLRP3/GSDMD axis." (PMID 33162822, 2020). "NLRP3 has been considered the gold standard of inflammasome signaling, as many NLRP3 inhibitors are under investigation in clinical trials for coronary artery disease and gout; more than 50 clinical studies are currently underway to elucidate the role of NLRP3 in various diseases." (PMID 33584697, 2020). "In addition, colchicine also inhibits NLRP3 inflammasome, which is a key mechanism of inflammation in gout, and surprisingly vascular diseases." (PMID 33133323, 2020). "However, this dogma regarding the central role of NLRP3 in gout has been challenged 23, 24, although IL-1β remains a crucial cytokine in the development of the disease." (PMID 32104502, 2020). "Our previous research demonstrated that the potential anti-gouty arthritis effect of QZTBD could be attributed to the inhibition of the activation of the NLRP3 inflammasome and the production of downstream proinflammatory cytokines." (PMID 33603667, 2020). "NLRP3 inflammasome and IL-1β are important inflammatory triggers during gout flare." (PMID 33365024, 2020). "As MSU crystal can activate the NLRP3 inflammasome and IL‐1β secretion to trigger the gout flare." (PMID 32656909, 2020). "Simiao decoction could reduce gut inflammatory cytokines through inhibiting the NLRP3 inflammasome which was important for gout-induced inflammation." (PMID 32670069, 2020). "Moreover, our results further show that wedelolactone can be used to treat MSU‐induced peritonitis and gouty arthritis probably by suppressing NLRP3 activation in vivo." (PMID 32656909, 2020). "The efficacy of selective NLRP3 inhibitors for the treatment of NLRP3-related inflammatory diseases, such as neurodegenerative diseases, gouty arthritis, CAPS and metabolic disease, has been widely demonstrated in several preclinical models and ex-vivo systems." (PMID 32560261, 2020). "Similarly, the accumulation of monosodium urate during gout can activate the NLRP3 inflammasome in macrophages." (PMID 32148650, 2020).
gout (continued). "Furthermore, oridonin inhibited IL‐1β production in NLRP3‐dependent mouse models of peritonitis and gouty arthritis." (PMID 32770571, 2020). "The mechanism of action may be that it interferes with the assembly or activation of the NLRP3 inflammatory complex by downregulating NLRP3 and caspase-1 proteins and then antagonizing the inflammatory response of gout." (PMID 32419834, 2020). "IL-1β is a key cytokine in gout inflammation considering the importance of NLRP3." (PMID 30914954, 2019). "In this study, we investigated whether EGCG could suppress the activation of the NLRP3 inflammasome in macrophages in order to pursue the possibility of its therapeutic application for NLRP3-mediated diseases such as gout." (PMID 31174271, 2019). "Thus, OLT1177 specifically prevents NLRP3 inflammasome formation and has the potential to treat NLRP3-related diseases, especially acute gout flares." (PMID 30755589, 2019). "Furthermore, a recent advance has been the discovery of attenuated activation of the NLRP3 inflammasome in colchicine-treated neutrophils and macrophages in response to monosodium urate crystals in the setting of gout." (PMID 31357404, 2019). "One study has shown that sulforaphane (1-isothiocyanato-4-methylsulfinylbutane), a natural dietary isothiocyanate derivative, abundant in cruciferous vegetables, exerted anti-inflammatory effects on gouty arthritis via direct inhibition of NLRP3 inflammasome signaling." (PMID 31200447, 2019). "Therefore, we further examined IL-1β release in gout via the NF-κB and the NLRP3 signaling pathways, respectively, to explore the mechanism of the antigout effect of chicory extract." (PMID 31590257, 2019). "Current therapeutic strategies to target IL-1β have proven successful for alleviating the symptoms of gout in clinical studies, suggesting that targeting the NLRP3 inflammasome may have a critical impact on gout treatment." (PMID 31174271, 2019). "However, expression of the components of the NLRP3 inflammasome were unaffected by priming or activation of the inflammasome, nor were these expression levels differentially regulated in gout patients." (PMID 30761138, 2019). "The potential anti-gouty arthritis effect of QZTB may be attributed to the inhibition of NLRP3 inflammasome and downstream proinflammatory cytokines (IL-1β and TNF-α) levels." (PMID 31885675, 2019). "Altogether, these data suggest that FADD secretion in the synovial fluid from gout patients might result from NLRP3 inflammasome activation by MSU crystals." (PMID 30804327, 2019). "The first step of nuclear factor kappa-B (NF-κB) activation is required to stimulate the expression of pro-IL-1β, and the maturation of IL-1β regulated by the NBD leucine-rich family (NLR) pyrin-containing 3 (NLRP3) inflammasome is the second key step in the initiation of gout flare." (PMID 31590257, 2019). "As a crucial element of the innate immune system, the NLRP3 inflammasome is not only an important component in host defense against pathogens but is also involved in the progression of several inflammatory human diseases, such as gout and type 2 diabetes." (PMID 31824450, 2019). "Finally, we established human soluble FADD as a new marker of joint inflammation in gout and rheumatoid arthritis, two rheumatic diseases involving the NLRP3 inflammasome." (PMID 30804327, 2019). "We investigated whether the inhibitory effects of EGCG on MSU crystal-induced NLRP3 inflammasome activation resulted in the prevention of gouty inflammation in an acute gout mouse model." (PMID 31174271, 2019). "Meloxicam could also decrease the mRNA and protein expression levels of NLRP3 in ankle joints in MSU-induced gouty arthritis rats." (PMID 31885675, 2019). "Therefore, it is essential to develop medical treatments for gout considering both the NF-κB and NLRP3 signaling pathways." (PMID 31590257, 2019).
gout (continued). "Gout is caused by precipitation of uric acid from the blood into insoluble crystals of monosodium urate (MSU) that can accumulate in joints and activate the NLRP3 inflammasome resulting in secretion of IL-1β." (PMID 30761138, 2019). "Therefore, we searched for orally available small-molecule drugs for gout treatment that inhibit the NLRP3 inflammasome, thereby blocking the production of active IL-1β." (PMID 31174271, 2019). "On this basis, the effective mechanism of chicory extract in gout through the NF-κB and the NLRP3 signaling pathways could be further explored." (PMID 31590257, 2019). "In addition, the aberrant NLRP3 inflammasome activation contributes to the progress of several human diseases, such as type 2 diabetes (T2D), atherosclerosis, Gout, and neurodegenerative diseases." (PMID 29959312, 2018). "We also determined whether the SNPs altered the expression of components of the NLRP3-IL11β signaling pathway in peripheral blood from the patients with gout and investigated the clinical relevance of these SNPs in relation to the development of GA." (PMID 29214547, 2018). "More importantly, TR could prevent or treat NLRP3‐dependent inflammatory diseases in mice models and was also active ex vivo for samples from patients with gout." (PMID 29531021, 2018). "It has been confirmed that NLRP3 inflammasome participated the development of gouty arthritis." (PMID 29214547, 2018). "Importantly, Ori has both preventive or therapeutic effects on mouse models of peritonitis, gouty arthritis and type 2 diabetes, via inhibition of NLRP3 activation." (PMID 29959312, 2018). "On that basis, we hypothesized that procyanidins, a safe and effective natural product, might attenuate gout pain by inhibiting NLRP3 inflammasome activation and IL-1β maturation in macrophages." (PMID 28376889, 2017). "However, the discovery that the NLRP3 inflammasome is activated by MSU crystals and associated with gout highlights the role of NLRP3 inflammasomes in sterile inflammatory diseases." (PMID 29259717, 2017). "We examined whether CAPE could suppress uric acid crystals-induced NLRP3 inflammasome activation in gout." (PMID 27934918, 2016). "Studies on gout pathogenesis have demonstrated that a single crystal of sodium urate can change NLRP3 configuration, resulting in NLRP3 activation and release of a large number of proinflammatory cytokines, including IL-1β, which participate in the pathogenesis of arthritis." (PMID 27034595, 2016). "The NLRP3 inflammasome, composed of NLRP3, the adaptor protein ASC, and caspase-1, is closely linked to the pathogenesis of various metabolic diseases including gouty arthritis." (PMID 27934918, 2016). "In addition, the suppressive effects of CAPE on gout were mediated by its blocking NLRP3 inflammasome activation in the mouse foot." (PMID 27934918, 2016). "Next, we investigated whether CAPE’s suppression of NLRP3 inflammasome could be applied to treat gout." (PMID 27934918, 2016). "Furthermore, the results suggest the preventive or therapeutic strategy for NLRP3-related inflammatory diseases such as gouty arthritis using orally available small molecules." (PMID 27934918, 2016). "IL-1 inhibition represents an alternative for patients with gout with failure of or intolerance to standard medications, because the main mechanism of crystal-induced inflammation is the activation of NLRP3 inflammasome and the consequent excessive production of IL-1β." (PMID 25758134, 2015). "They suggest that synovial fibroblasts may participate in the secretion of IL-1β via NLRP3 inflammasome formation, which could make synovial fibroblasts a potential therapeutic target for gout." (PMID 25897296, 2015). "Although MSU has been described as a causative agent in gout for more than 100 years, its mechanism of action was not understood until the discovery of NLRP3 a decade ago." (PMID 25897296, 2015).
gout (continued). "The C-allele of rs7512998 has previously been shown to be more common in gout patients compared with controls, although 16 other NLRP3 gene polymorphisms showed no such association." (PMID 26523150, 2015). "The results indicate that targeting the NLRP3 inflammasome in FLS may be a relevant therapeutic strategy in the treatment of gout." (PMID 25897296, 2015). "The in vivo relevance of the NLRP3 inflammasome is well documented by its role in hereditary autoinflammatory syndromes and by its role in the progression of metabolic diseases that are accompanied with inflammation such as atherosclerosis, diabetes and gout." (PMID 23666718, 2013). "Because the NLRP3 inflammasome also drives IL-1 β maturation and secretion in gout, another disease of metabolic dysregulation, the authors propose that the NLRP3 inflammasome contributes to the pathogenesis of T2DM and gout by functioning as a sensor for metabolic stress." (PMID 23060876, 2012). "Our findings suggest that the NLRP3 inflammasome may be activated more readily in patients with gout than in healthy controls." (PMID 22762240, 2012). "Recent studies suggest that blockade of the NLRP3 (cryopyrin) inflammasome interleukin 1β (IL1β) pathway may offer a new treatment strategy for gout." (PMID 19635719, 2009). "The pathogenesis of gouty arthritis, characterized by the MSU crystal deposition in the joints associated with acute flares, has been associated with NOD-, LRR-, and pyrin domain-containing protein 3 (NLRP3) inflammasome activation and subsequent amplification of the inflammatory response." (PMID 40493163, 2025). "Similarly, uric acid, a breakdown product of purines that is elevated in both gout and obesity-related metabolic syndrome, crystallizes within macrophages and renal cells, directly activating the NLRP3 inflammasome and thereby linking metabolic dysregulation to both vascular and kidney inflammation." (PMID 41488670, 2025). "Given that monosodium urate crystals drive gouty inflammation primarily through NLRP3 inflammasome activation and the subsequent release of IL-1β and IL-18, the suppressive effects of GDF15 on these mediators suggest a potential regulatory role in modulating gout-associated inflammatory responses." (PMID 40722837, 2025). "Additionally, the accumulation of hydroxyapatite crystals in osteoarthritis and monosodium urate in gout may activate the NLRP3 inflammasome, leading to inflammation and joint disorders." (PMID 38248332, 2024). "Interestingly, after intraperitoneal MSU infusion, these mice also showed decreased neutrophil infiltration, indicating that the NLRP3 plasma membrane plays an important mediating role between the recognized gout-related stimuli and the additional clinical signs of acute gout attacks." (PMID 38248332, 2024). "Therefore, chronic H. pylori infection is likely to contribute to the activation of NLRP3 inflammasome in gout flare by providing the first signal, which makes NLRP3 inflammasome a potential bridge between infections inflammation and non-infectious inflammation." (PMID 38678252, 2024). "Besides it also effectively downregulated NLRP3 in synovial cells of gout patients." (PMID 38421496, 2024). "Therefore, PPAR-γ could be a therapeutic target for NLRP3 inflammasome-mediated diseases, including gout." (PMID 37111279, 2023). "Therefore, chemokine CXCL12 and its receptor CXCR4 might be considered to be potent therapeutic targets in uric acid-induced NLRP3 inflammasome activation in gout patients." (PMID 36979628, 2023). "Moreover, ROS also acts as an important contributor to NLRP3 inflammasome activation during gout." (PMID 37464384, 2023). "MSU crystals then activate monocytes and macrophages, resulting in the NLRP3 (NLR family pyrin domain containing 3) inflammasome-mediated release of IL-1B and proinflammatory cytokines and recruitment of neutrophils to the site of crystal deposition, driving the clinical features of gout." (PMID 36987445, 2023).
gout (continued). "However, it remains uninvestigated whether Drp1-dependent mitochondrial fission and NLRP3 inflammasome activation are involved in gouty arthritis." (PMID 37488647, 2023). "Furthermore, by combining and synthesizing the results of multiple studies that investigate TCM’s inhibitory effects on signaling pathways like NLRP3, along with its positive effects on gout, we are optimistic about substantial progress in the field of anti-gout TCM." (PMID 38094893, 2023). "Therefore, our work suggests that EA may attenuate TRPV1 overexpression in sensory neurons of gout model mice through mechanisms involving the reduction of NLRP3 inflammasome activation." (PMID 37464384, 2023). "In addition to its proven proficiency in treating gouty arthritis and pericarditis, colchicine, a widespread drug, has proven recently to be an effective anti-inflammatory compound by blocking NLRP3 inflammasome activity and suppressing IL-1β and IL-18 secretion." (PMID 37175869, 2023). "Moreover, catechins exhibit potent free radical scavenging activity, significantly reducing the secretion of IL-1β and IL-6 in C57BL/6 mice induced by MSU crystals, while inhibiting the activation of the NLRP3 inflammasome, thus effectively reducing the likelihood of developing gout in patients." (PMID 37519890, 2023). "Furthermore, studies have shown that the expression of miR-223-3p is significantly down-regulated in the mouse model of pouch synovium with the expression of NLRP3 inhibited by the overexpression of miR-223-3p, ultimately alleviating the inflammatory effect of gout." (PMID 37426193, 2023). "However, the effect of NLRP3 inflammasome on gout’s overall pathological process is unclear." (PMID 36569836, 2022). "Therefore, dapansutrile may attenuate inflammation and reduces pyroptosis by inhibiting the NLRP3 inflammasome to treat gouty arthritis." (PMID 36105284, 2022). "Therefore, allosteric modulation of P2X7R may be an effective strategy to block NLRP3 inflammasome activation for the treatment of gout." (PMID 36052144, 2022). "Similarly, recent studies have found that some natural products alleviated alcoholic liver injury and gouty arthritis by inhibiting NLRP3 inflammasome, which has guiding significance for the development and clinical application of alcoholic liver injury and gouty arthritis by targeting NLRP3." (PMID 36176434, 2022). "Furthermore, neoastilbin could exert anti-gout effects by inhibiting the activation of the NF-κB and NLRP3 inflammasome pathways both in vivo and in vitro." (PMID 35684415, 2022). "However, it remains unclear how corilagin regulates the NLRP3 inflammasome to relieve gouty arthritis." (PMID 36299604, 2022). "Therefore, we speculate that the triterpenoid-enriched fraction from CP (CPT) may be the active ingredients to ameliorate gout through inhibiting NLRP3 inflammasome activation." (PMID 35047046, 2022). "Therefore, we speculate that CPT may be the effective substances to suppress NLRP3 inflammasome activation via PI3K-AKT-mTOR-dependent autophagy to ameliorate gout." (PMID 35047046, 2022). "Hence, EC might be a new and safe candidate for the clinical prevention and treatment of gouty arthritis, as well as NLRP3-related diseases." (PMID 35462936, 2022). "In addition, NLRP3 interacts with cAMP to promote gout flare." (PMID 35411030, 2022). "NLRP3 is an intracellular sensor that detects a broad range of pathogen-associated molecular patterns (PAMP) and danger-associated molecule patterns (DAMP) and is implicated in the pathogenesis of several autoinflammatory diseases, including arthritis, gout, diabetes, obesity, and AD." (PMID 35741054, 2022). "Notably, EC could significantly reduce the expression of NLRP3 inflammasome key proteins in MSU-induced gout inflammation." (PMID 35462936, 2022).